CTLA4 (cytotoxic T-lymphocyte associated protein 4)
Diseases named in the same sentence as CTLA4 in open-access papers (continued):
Sharing a sentence is not in itself a finding about the gene and the disease.
tumor (continued). "In that study, the combination of CSF-1R blockade with anti-PD-1 or anti-CTLA-4 blocking antibody improved anti-tumor immunity in mice refractory to ICB." (PMID 33924237, 2021). "Manipulations of the immune checkpoints PD-1 and CTLA-4 are among the immune escape mechanisms of cancer cells and the PD-1/PD-L1 pathway seems to play a pivotal role in the development of a tumor-tolerant TME in BTC." (PMID 33922362, 2021). "ICIs can enhance anti-tumor T cell reactivity and promote immune control over the cancerous cells by blocking cytotoxic T-lymphocyte antigen 4 (CTLA-4) or the combination of PD-1 and PD-L1." (PMID 34867321, 2021). "The β-catenin pathway is also involved in other mechanisms of immune resistance, namely immune suppression, whereby tumor cells with hyperactive signaling acquire the expression of CTLA-4 and can secrete IL-10." (PMID 33535559, 2021). "Intentionally subradical (<10% of tumor volume) HIFU together with anti-CTLA-4 and anti-PD-L1 resulted in an impressive abscopal effect." (PMID 34307177, 2021). "CTLA-4 was the first negative regulator of T cell activation identified in the context of antitumor immunity, and its blockade using mAbs triggers tumor regression and a durable antitumor immunity in preclinical models." (PMID 33804419, 2021). "Inhibition of tumor glycolysis elevated available glucose levels in the TME and promoted the ability of CTLA-4 blockade to induce Treg cell fragility associated with IFN-γ production and development of anti-tumor immunity." (PMID 34539668, 2021). "By developing anti-CTLA-4 antibodies, the aim was to remove the brakes from T cells to enhance anti-tumor T-cell response." (PMID 35008230, 2021). "Our data show that LL/2 subcutaneous tumor growth is resistant to anti-PD-1 and anti-CTLA-4 antibody therapies." (PMID 34411144, 2021). "Hypoxic signals increase resistance to T cell-mediated killing by enhancing CTLA-4 expression on CD8+ T cells, as well as recruiting Tregs, myeloid-derived suppressor cells, and tumor associated macrophages (TAMs) into the TME." (PMID 33816258, 2021). "As expected, a higher PSMC5 level was significantly linked to expression of CD274 (PD-L1), CTLA-4, and IDO1 in CRC tumor cells, indicating a potential role of inhibiting PSMC5 in immune checkpoint blockade (ICB) therapy." (PMID 34336824, 2021). "This condition promotes the development of specific tumor vaccines, and tumor targeted therapy strategies, such as anti-CTLA-4 and anti-PD-1, have been applied in clinic in recent years as precision medicine and achieved many successes." (PMID 33921058, 2021). "The T lymphocytes most often described as tumour‐promoting are the immune‐suppressive T regulatory cells (Tregs) in part mediated through cell contact through CTLA4 (cytotoxic T lymphocyte antigen 4)." (PMID 33773029, 2021). "The combination of bicarbonate therapy neutralizing tumor acidity with anti-CTLA-4 or anti-PD1 improved antitumor responses." (PMID 34858835, 2021). "The deactivation promoted a “hot” tumor microenvironment and enhanced the sensitivity to immune checkpoint blockade with antibody against the cytotoxic T-lymphocyte antigen 4 (CTLA-4)." (PMID 33923750, 2021). "Low levels of CD80 expression serve as a mechanism of tumor escape from immune surveillance due to a higher affinity and, therefore, preferential binding of CTLA-4 to CD80 compared with that for CD28." (PMID 33923750, 2021). "Especially, inhibitory molecules TIGIT, CTLA4, and co-stimulatory molecules ICOS, CD28 whose expression was higher in tumor-associated Treg cells compared to that from normal tissues, were highly expressed in decidual Tregs." (PMID 34168655, 2021). "The combination of CTLA‐4 and PD‐1 inhibitor can fully release the killing function of T cells and avoid the phenomenon of tumor escape in the initial stage of immunity and immune response stage." (PMID 34747149, 2021).
tumor (continued). "Initial studies have shown that CTLA-4 can be expressed in tumor-infiltrating lymphocytes, leading to the attenuation of anti-tumoral immune responses." (PMID 34067631, 2021). "To date, all seven FDA-approved ICBs target immune checkpoints CTLA-4 and PD-1/PD-L1 that are co-opted by tumor cells to evade immunosurveillance." (PMID 34830176, 2021). "After detecting an accumulation of activated Treg strongly expressing CTLA-4 in lungs with tumor nodules, the authors showed that these cells suppress anti-tumor responses." (PMID 34276690, 2021). "Given that PD-1 and CTLA-4 participate in different processes of T cell recognition and cytotoxic T cell reinvigoration, combinations of antibodies against PD-1 and CTLA-4 are of great potential to induce tumor regression synergistically." (PMID 34924562, 2021). "Currently, immunotherapy for advanced LUAD mainly uses checkpoint inhibitors, such as PD-1/PD-L1 inhibitors and CTLA-4 inhibitors, to activate the patient’s own immune system to kill tumor cells." (PMID 34552612, 2021). "We further confirmed a reduction of tumor infiltrating Tregs with the addition of anti-CTLA-4 to RT+BEMPEG, as compared to RT+BEMPEG alone." (PMID 33937052, 2021). "For instance, Chae and colleagues developed nanocarrier-mediated delivery of two ICIs (i.e., anti-CTLA-4 together with anti-PD-1) with a synergic effect; thus, this treatment showed a slower tumor growth and longer mice survival compared to the monotherapy." (PMID 33800368, 2021). "By blocking the interaction between CTLA-4 and its ligands, T cells can remain active to recognize and target tumor cells." (PMID 34298809, 2021). "Immune checkpoints such as cytotoxic T lymphocyte-associated antigen 4 (CTLA4) and programmed cell death ligand-1 (PD-L1) have been shown to impede anti-tumor immunity, leading to the invasion of host immune attack." (PMID 33668805, 2021). "As one of the most common ICIs, anti-CTLA4 antibodies such as ipilimumab and tremelimumab have enhanced the anti-tumor immune response in both preclinical and clinical research and achieved unprecedented success." (PMID 34178691, 2021). "Immune checkpoint inhibitors (ICIs) targeting the PD-1/PD-L1 axis or CTLA-4 can restore the anti-tumoral function of CTLs and impede tumor progression." (PMID 34952595, 2021). "Studies have shown that the expression of immune checkpoints such as PD-1L, TIM3, TIGIT, and CTLA4 can affect tumor progression and thus change patient prognosis." (PMID 34484330, 2021). "TIDE is a computational method that predicts the outcome of tumor patients treated with anti-PD1 or anti-CTLA4 and calculates the score by evaluating the degree of T cell dysfunction." (PMID 33869027, 2021). "A pH-sensitive CTLA-4 antibody has been shown to reduce cancer immunotherapy-related adverse events with increased anti-cancer activity in the tumor site." (PMID 34806028, 2021). "Tumor-derived IL-33 increases the number and function of CD103+CD8+ TILs, and a combination of IL-33 with the CTLA-4 and PD-1 immune checkpoint blockades synergistically prolonged the survival of tumor-bearing mice." (PMID 33467606, 2021). "We also report that the IM subtype was characterized by a high CTLA-4 expression of intT and strml T-cells in the IHC analysis, associated with a high PDL-1 positivity in the tumor and increased PD1+ TILs density." (PMID 34944876, 2021). "CTLA4 is highly increased in the tumor immune microenvironment, particularly on T regulatory cells (Tregs) upon activation." (PMID 34869309, 2021). "PD-1 expression on the tumor-specific T cells following anti-CTLA-4 alone or dual therapy remained slightly elevated in the tumor compared to the spleen 14 days after treatment." (PMID 34162858, 2021). "Targeting this receptor appears to be a strategy for improving anti-tumor immunotherapy responses, especially in combination with CTLA-4 and PD-1." (PMID 34073258, 2021).
tumor (continued). "In multiple murine tumor models, A2aR inhibition synergized with anti-PD1, anti-TIM3, and anti-CTLA4 antibodies to improve survival and reduce tumor metastasis." (PMID 34222022, 2021). "Another DNA vaccine was designed by fusing the extracellular domain of CTLA-4 to HER-2/Neu to facilitate the detection of tumor antigens by APCs." (PMID 34729098, 2021). "We also uncovered that the high-risk cluster exhibited elevated expression levels of PD1, PDL1, CTLA4, LAG3, and TIGIT compared to the low-risk counterpart, supporting the contribution of hypoxia to the tumor immune escape in HCC." (PMID 34917132, 2021). "One of the representative reasons is that tumor cells establish a clever escape strategy from anti-tumor immunity mediated by the signaling of PD-1/PD-L1 or CTLA-4." (PMID 34830754, 2021). "In particular, transfer of the taxa Bacteroides thetaiotaomicron, Bacteroides fragilis, and Burkholderia capacia was able to restore anti-tumor activity of anti-CTLA-4 antibodies in germ-free mice." (PMID 34307839, 2021). "Mice of groups B and C, which received either [177Lu]Lu-DOTA-folate or the anti-CTLA-4 antibody, respectively, showed only ~ 10–40% delayed tumor growth compared with the controls." (PMID 33078260, 2021). "The effect of CTLA-4 inhibition against HCC was studied in a phase 2 study using anti-CTLA4 (tremelimumab) plus tumor ablation therapy." (PMID 34696292, 2021). "As CTLA4 promotes the suppression of the immune system, its high expression can lead to faster progression or even to the development of neoplasms." (PMID 33802937, 2021). "PD1 or CTLA4 blocking results in deactivation of Tregs and other immunosuppressive mechanisms and consequently activated anti-tumor T cells for defense." (PMID 34485117, 2021). "Simultaneous blockade of both CTLA-4 and PD-1 reverses T cell dysfunction and generates more durable anti-tumor immunity than either therapy alone." (PMID 34446702, 2021). "These morpholinos have proven effective in limiting tumor growth in immune-competent hosts when combined with radiotherapy, chemotherapy, or an immune checkpoint inhibitor targeting CTLA4 on T cells." (PMID 33925464, 2021). "ICIs intent to reverse this blockade of the T-cells by either binding to CTLA-4 (Ipilimumab), PD-1 (Pembrolizumab, Nivolumab) or PD-L1 (Avelumab), unblocking an anti-tumour response against MCC." (PMID 34445385, 2021). "Both cell lines generated tumors growing progressively in untreated mice, whereas treatment with anti-PD-1 or anti-CTLA-4 antibodies inhibited ASB-XIV tumor growth." (PMID 34771674, 2021). "Monoclonal antibodies that block PD-1, PD-L1, and CTLA-4 have each been found to demonstrate persuasive anti-tumor effects." (PMID 34745002, 2021). "In contrast with anti-CTLA-4, PD-1 blockade exerts a limited impact on the on-treatment dynamics of tumor infiltrating CD4 + effector T cells in murine models." (PMID 33602280, 2021). "Mice bearing a subcutaneous colorectal CT26 tumor received three times different immunotherapy treatments (PD1 or CTLA4 or combined)." (PMID 34212037, 2021). "Tumor cells are able to avoid cellular immune response and elimination by the following mechanism: certain antigens (e.g., CTLA-4, PD-1) that are expressed on the surface of T-cells bind to their corresponding ligands located on the tumor surface." (PMID 34576168, 2021). "While standard therapies have focused on PD-1 and CTLA-4 blockade, additional immune checkpoints have shown promise in promoting anti-tumor immunity." (PMID 33708224, 2021). "It has been also shown that combination of PD-1 and CTLA-4 blockade directly triggers a Th1-like response that activates the tumor-infiltrating CD103+ DCs, which are highly efficient at presenting tumor antigens and show enhanced IL-12 production." (PMID 33777008, 2021). "In contrast, in the immunologically hot CT26-HER2 tumor, the checkpoint molecules and effectors, including CTLA-4 and Ido1, were at high levels; the tumor responded to checkpoint blockade." (PMID 34578328, 2021).
tumor (continued). "Peripheral blood T cells of dogs with neoplasia have demonstrated expression of CTLA-4, making this a potential therapeutic target in canine patients." (PMID 34869014, 2021). "In contrast, checkpoint inhibition with anti-CTLA-4 enhanced overall survival but only temporarily delayed primary tumor growth." (PMID 33411055, 2021). "In particular, when Δt=1 week, the administered doses of anti-CTLA4 needed to eradicate the tumor passes from 12 for the mono-therapy to 9 for the combination therapy." (PMID 35008298, 2021). "First, we tested the therapeutic efficacy of co-administration of α-IL-6 and anti-CTLA-4 antibody (α-CTLA-4) on LLC tumor growth in subcutaneous model." (PMID 34093869, 2021). "The high expression of CTLA-4 in BC cells allows the tumor to suppress the maturation and function of DC and, consequently, decreases T cells function." (PMID 34829916, 2021). "In the anti-CTLA-4/PD-1/PD-L1 GEO cohort (GSE91061 and GSE135222), higher DMS in tumor patients was associated with a stronger immune response and higher therapeutic benefits." (PMID 34552879, 2021). "Checkpoint inhibitors are antibodies that target cytotoxic T lymphocyte Antigen 4 (CTLA-4), PD-1, and programmed death ligand-1 (PD-L1) and thereby block the inhibition of the immune response by the tumor and its microenvironment." (PMID 34067112, 2021). "Using immune checkpoint inhibitors (ICIs), particularly PD-1, PD-L1 and CTLA-4 have become pivotal drugs in tumor-targeted molecular therapy with a brighter therapeutic future." (PMID 34777359, 2021). "Mechanistically, ATOR-1015 localized to the tumor area enriched in CTLA-4+ TA-Tregs and reduced their frequency but increased the number and activation of CD8+ T cells." (PMID 33924428, 2021). "CTLA-4 significantly increased the volume and weight of transplanted tumor, while TGF-β neutralization can partially inhibit these effects of CTLA-4." (PMID 34553071, 2021). "CTLA4 is a receptor expressed on tumor cells, regulatory T cells, and exhausted T cells that negatively regulate CD8+ T cells." (PMID 33564739, 2021). "A recent study also used sub-therapeutic doses of IDO-targeting S. typhimurium along with anti-PD-1/CTLA-4 antibodies to treat LLC1-tumor bearing mice." (PMID 34203478, 2021). "Collectively, these findings demonstrate that homeostasis of the intestinal microbiota potentially promotes the blocking effect of PD-1/PD-L1 and CTLA-4, improves response to ICIs, and promotes tumor control." (PMID 34125407, 2021). "CTLA-4 blockade synergized with different forms of thermal tumor ablation, resulting in significant amounts of active tumor-specific T cells and the ability to reject secondary or re-challenged tumors." (PMID 33936033, 2021). "Blockade of inhibitory checkpoints: Anti-PD-1/Anti-PD-L1/Anti-CTLA-4/Other ICIs, enabling tumor-reactive T cells to overcome regulatory inhibitory mechanisms." (PMID 34692696, 2021). "Α 4-1BB attenuated proliferation of Tregs, dampens the Tregs fraction of TIL, counteracts anti-CTLA4's expansion of absolute numbers of Treg in the tumor, and declines CTLA-4 and PD-1 expression by Tregs." (PMID 34267616, 2021). "The aim of this study is to investigate the expression of the PD-1/PD-L1 pathway and CTLA-4 in the tumor microenvironment of epSCCs to assess the feasibility of an immunotherapeutic approach." (PMID 34359249, 2021). "The combination of PL1-OX40 (ψ) + anti-OX40 with anti-PD-1 + anti-CTLA-4 Ab treatment dramatically inhibited tumor growth and prolonged survival in comparison to treatment with PBS or anti-PD-1 + anti-CTLA-4 Ab." (PMID 34907171, 2021). "Analysis of the relationship between risk score and the expression of crucial immune checkpoint genes revealed that high-risk patients had higher CTLA4, CD83, B3H7, OX40L, and GEM levels in the tumor microenvironment." (PMID 33718151, 2021). "Blocking the negative regulators of PD-1 and CTLA4 that impair CD28 signaling to inhibit T cell release facilitates anti-tumor activity." (PMID 34208157, 2021).
tumor (continued). "ZDHHC16 expression was significantly positive associated with clinicopathological stage, tumor grade and ICB immunotherapy key genes (i.e., CD274, CTLA4, HAVCR2 and PDCD1, etc.)." (PMID 33794886, 2021). "Injections of monoclonal antibodies (mAb) blocking immunological checkpoints, such as CTLA-4, PD-1, and PD-L1, enhance antitumor immunity and lead to tumor rejection." (PMID 33419027, 2021). "CTLA-4-mediated suppression of anti-tumor immunity is thought to occur primarily in secondary lymphoid organs, where T-cell activation also occurs." (PMID 33923423, 2021). "Studies have shown that CTLA-4 or PD-1 inhibitors can reduce tumor vascular density, improve vascular perfusion, relieve hypoxia of tumor tissue, normalize blood vessels, and reduce the immunosuppressive effect of Treg, TAMS, and MDSCs." (PMID 34532293, 2021). "By combining KD with ICB therapy (anti–PD-1 or anti–CTLA-4) the anti-tumour effects of the treatment were potentiated even in tumours that showed previous resistance to ICB drugs." (PMID 34658896, 2021). "UCNP-Ce6-R837 combined with CTLA-4 blockade not only displayed excellent efficacy in eliminating primary tumor but also resulted in strong antitumor immunities to inhibit the growth of distant tumors." (PMID 33537087, 2021). "Our results identified a CTLA4/miR-20b-5p axis in the control of immune infiltration in the tumor microenvironment." (PMID 34336706, 2021). "Recently, CSC-targeted DC vaccines have been reported to enhance the elimination of melanoma CSCs in a mouse tumor model with a combination of PD-L1 and CTLA-4 blockades, with an enhanced CD8+ T cell response, increased IFN-γ and inhibited TGF-β expression." (PMID 34235155, 2021). "Induction of immune checkpoints, such as cytotoxic T lymphocyte antigen 4 (CTLA-4), programmed cell death protein 1 (PD-1) and its ligand, PD-L1, mediates tumor immune evasion." (PMID 35003065, 2021). "Ipilimumab, an anti-CTLA-4 antibody, has demonstrated improved anti-tumor efficacy with enhanced immunity." (PMID 34858835, 2021). "Preclinical studies demonstrate that systemic effects of RT in priming a systemic anti-tumor T cell response are achieved more reliably when RT is combined with anti-CTLA-4 and/or anti-PD-1/PD-L1 checkpoint blockade." (PMID 33937052, 2021). "Compared with monotherapy, tumor-bearing mice administrated with combined treatment of vaccine and anti-CTLA-4 antibody exhibited significantly improved survival rate and reduced lung metastasis." (PMID 34959285, 2021). "A recent study showed that CTLA4, as a tumor suppressor gene, has a vital function in suppressing the immune responses of activated T lymphocytes." (PMID 33869632, 2021). "Combined blockade of IL-6 and CTLA-4 suppressed lung tumor growth in mice by increasing tumor-infiltrating CD8+ T cells and M1 macrophages." (PMID 34093869, 2021). "Preclinical assays showed that dual blockade of PD-1 and CTLA-4 combined with GM-CSF gene-transfected tumor cell vaccine (GVAX) in murine models of CRC resulted in tumor rejection in 100% of mice." (PMID 34944931, 2021). "In a preclinical study using an EMT6/P breast cancer mouse model, blocking cytotoxic T-lymphocyte antigen 4 (CTLA-4) inhibited tumor growth." (PMID 34771577, 2021). "Blockade of immune checkpoints by anti-CTLA-4 or anti-PD-1/anti-PD-L1 agents leads to T-cell activation, and it provides an effective approach for tumor immunotherapy." (PMID 34880877, 2021). "Immune checkpoint inhibitors (pembrolizumab and nivolumab as anti-PD1; atezolizumab as anti-PD-L1; ipilimumab as anti-CTLA4) became a successful strategy to enhance anti-tumor response in many malignancies." (PMID 34771694, 2021). "Studies have shown that CTLA-4 is closely related to tumor progression and treatment, and blocking the inhibitory effect of CTLA-4 can enhance the effective immune response against tumor cells." (PMID 34217372, 2021).